CXCR4 (C-X-C motif chemokine receptor 4)
Diseases named in the same sentence as CXCR4 in open-access papers (continued):
Sharing a sentence is not in itself a finding about the gene and the disease.
infection (continued). "We clearly found that those individuals with larger and predominant CXCR4-tropic reservoirs had more naive infection, consistent with a prior study, and more diverse reservoirs." (PMID 34228640, 2021). "Typically, only a small subset of peripheral Vδ2 T cells expresses the chemokine receptor CXCR4, but an increase in expression found in individuals with chronic infection raises the possibility that Vδ2 T cell may become susceptible to CXCR4-tropic viruses after initial infection." (PMID 32509594, 2020). "Of note, a CXCR4-tropic virus strain was used to focus on trans-infection occurrence rather than cis-infection as DCs are particularly resistant to infection by these strains." (PMID 32181159, 2020). "SMARTpool siRNA was transfected into monocyte-derived DCs (MDDCs) 48 h before infection with full-length CXCR4-tropic HIV-1 (R9) and cocultured with SUPT1 cells at 1:1 ratio." (PMID 32075937, 2020). "Infection with lentiviruses carrying the CXCR4 and SF1 genes was applied to construct CXCR4‐SF1‐ADSCs." (PMID 32181567, 2020). "Four days after infection with CXCR4-tropic HIV-1 NL4-330 at 0.1 multiplicity of infection (MOI), CMT showed no detectable expression of HIV-1 p24 protein." (PMID 32792548, 2020). "Next, we used lentiviral infection to construct different types of ADSCs, which were named Vector‐ADSCs, CXCR4‐ADSCs, SF1‐ADSCs and CXCR4‐SF1‐ADSCs; the Vector‐ADSCs were used as a negative control." (PMID 32181567, 2020). "As an alternative means to measure the level of activation in CD4+ T cells, infection with the CXCR4‐tropic HIV‐1 NLX virus was chosen as a biological model system." (PMID 31552706, 2019). "The potency and efficacy of SDF-1/54 against CXCR4 tropic HIV-1 strains were determined in single-cycle infection assays and multiple-cycle infection assays, respectively." (PMID 31540474, 2019). "Conversely, the replication of the CXCR4-tropic NL4.3 strain (after an initial increase up to day 7) underwent a drastic decrease becoming almost undetectable after 10 days post-infection." (PMID 31234437, 2019). "These cells were partially CD4+ and/or CXCR4+ before infection, and confirmed to be partially susceptible to HIV-1NL4−3 infection." (PMID 30761146, 2019). "At the HIV-1 context CXCR4 is used by the virus to enter the cell with X4 tropism, and in the late infection process, R5 tropism strains can transform into double-tropism strains, using both coreceptors to enter the cell." (PMID 31531340, 2019). "Further assays and analyses revealed that CD34+CD7+CXCR4+ cells can be quickly depleted as early as 1 week after infection of the subset, and this was accompanied by the emergence of rare CD34+CD7+CD4+ cells." (PMID 30761146, 2019). "Over the following decades, after the discovery of CD4 as the main virus receptor, further studies have demonstrated that the chemokines coreceptors CCR5 and CXCR4 play crucial duties in supporting infection of HIV-1 in target cells." (PMID 31234437, 2019). "To summarize, CCR5 strains induce chronic and productive infection in MDM whereas CXCR4-tropic strains induce abortive infection." (PMID 31234437, 2019). "CXC-type chemokine receptor 4 (CXCR4) is well known as a co-receptor for cellular entry and infection of human immunodeficiency virus type 1 (HIV-1)." (PMID 31412600, 2019). "ASC are known to have a CXCR4-dependent migratory window, when they preferentially home to the bone marrow following peripheral immunization or infection (36, –, 39)." (PMID 30333176, 2019). "While the CD4, CCR5, CXCR4 axis for cell-free infection has been the most studied, there are a plethora of reports suggesting that the cell-to-cell transmission of HIV-1 is significantly more efficient." (PMID 30619107, 2018). "As dual- or mixed-tropic viruses cannot be distinguished readily in phenotypic or genotypic assays, they are referred to as infections with DM tropism; however, clonal analyses can distinguish true dual-tropic virus from CXCR4-tropic (X4) virus." (PMID 30586365, 2018).
infection (continued). "Infection of cells with virus produced during transfection was inhibited through the use of the CXCR4 antagonist AMD3100, and thus the level of viral output in our analysis cannot be confounded by entry inhibition due to IFITM expression." (PMID 30266929, 2018). "We chose to induce IFITMs after X4-tropic HIV-1 NL4-3 entry and limit infections to a single round through the use of the CXCR4 antagonist AMD3100 after infection to mitigate the influence of IFITMs upon viral entry." (PMID 30266929, 2018). "Emergence of CXCR4 is much less common in subtype C, which accounts for approximately half of infections worldwide." (PMID 29970186, 2018). "This is further supported by the observation of relatively poor fitness of the CXCR4-using virus, with frequent observation of reversion to an infection dominated by R5 virus after maraviroc treatment was stopped." (PMID 30586365, 2018). "After successfully blocking HIV-1NL4-3 infection, we attempted to test the effect of the CXCR4 mutant P191A on restricting infection of other X4-tropic HIV-1 strains." (PMID 29872154, 2018). "We also found that DCs amplified infection of CXCR4 and CCR5-tropic isolates including transmitted founder (T/F) strains." (PMID 29293546, 2018). "Taken together, these results demonstrated that the replacement of endogenous CXCR4 with the P191A mutant significantly reduces HIV-1NL4-3 infection." (PMID 29872154, 2018). "At the site of infection/inflammation, CXCR4 plays a more nuanced role in modulating the immune response." (PMID 29734477, 2018). "Previous research has shown that HIF-1α enhance macrophage migration to the site of infection by increasing the expression of CXCR4 and decreasing CCR5 expression, which leads to macrophage retention in the area of infection." (PMID 29762526, 2018). "Chemokines that bind to either CXCR4 or CCR5 were shown to prevent infection by X4 and R5 HIV-1 particles, respectively, and, hence, are referred to as HIV suppressor factors." (PMID 28360196, 2017). "Previous reports demonstrated that infection of different cell types with HCMV has diverse effects on CXCR4." (PMID 28484459, 2017). "It has been proved that gp120 causes impairment of the T cell response to CXCL12-induced chemotaxis, whereas CXCL12 inhibits infection by CXCR4-tropic virus." (PMID 29085362, 2017). "Accordingly, the expression of the receptors for Ccl3 and Cxcl12, Ccr1 and Cxcr4, respectively, were significantly upregulated by the interaction of low diet and infection (p < 0.05)." (PMID 28397794, 2017). "In sum, consistent with prior results, CCR5-tropic viruses consistently demonstrated a restricted pattern of infection of more differentiated progenitors that contrasts with the wide range of progenitors targeted by CXCR4-tropic and VSV-G-pseudotyped viruses." (PMID 28732051, 2017). "The p24 ELISA results showed that, compared with unmodified cells, the X4R5-gene modified cells produced less p24, indicating these cells were resistant to either CXCR4-tropic HIV-1NL4-3 or CCR5-tropic HIV-1YU-2 infection." (PMID 28904745, 2017). "Whilst we did not detect any changes in CCR7 gene expression in this early infection, gene expression of CXCR4 was downregulated." (PMID 28572564, 2017). "Campbell and Spector identified that when resting CD4+ T cells were exposed to CCL2, upregulation of CXCR4 expression occurred, and the elevated CXCR4 expression increased infection by CXCR4-tropic HIV." (PMID 29085362, 2017). "CXCR4-dependent HIV variants accumulate in patients with disease progression, whereas CCR5-dependent variants dominate in early infection." (PMID 29056666, 2017). "Preferential infection of these cells is associated, in part, with high surface expression of CCR5, CXCR4, and α4β7." (PMID 28509877, 2017). "CCR5 is exclusively utilized in the initial infection of HIV-1, whereas CXCR4-tropic strains are rarely observed in the early infection and only become dominant afterward." (PMID 28484468, 2017).
infection (continued). "As the dual-tropic R3A can also utilize CXCR4 for infection, we found R3A replication in CD4 T cells wasn’t significantly affected by TAK-779 treatment, as measured by intracellular p24 staining or extracellular HIV-1 RT levels." (PMID 27026376, 2016). "Env is a 3-kb HIV gene that encodes the envelope glycoprotein, which triggers infection by binding CD4 and a co-receptor (either CXCR4 or CCR5) and is the primary target for HIV vaccine development." (PMID 26789840, 2016). "One of the best recognized pathological function of CXCR4 is its role as a co-receptor during infection with human immunodeficiency virus (HIV)-1 and the ability of CXCL12 to interfere in the infection process, at least in vitro." (PMID 27664068, 2016). "The virulent nature of subtype D is believed to be due to its ability to use both the CXCR4 and CCR5 receptors simultaneously throughout the infection and as a result being associated with faster disease progression." (PMID 26871567, 2016). "The observed downregulation of CXCR4 at early time points of infection is most probably attributed to other factors." (PMID 27955674, 2016). "The best recognized pathological function of CXCR4 is its role as a co-receptor during infection with HIV-1." (PMID 27664068, 2016). "We then monitored CXCR4 surface expression in mock- and lytically-infected cells at early (24 hpi) and late (96 hpi) time points of infection." (PMID 27955674, 2016). "At late time points of infection (96 hpi) CXCR4 surface expression was significantly downregulated in TB40E/IE2eYFP-infected HUVEC, whereas in TB40E/IE2eYFP-delUS28-infected HUVEC, CXCR4 surface expression was restored to mock level." (PMID 27955674, 2016). "This indicates that US28 a critical factor involved in attenuation of CXCR4 surface expression in particular at late time points of infection, which also correlates with the late expression kinetic of US28." (PMID 27955674, 2016). "PleCs counts were increased upon infection in both type of mice but neither the levels nor the composition was significantly different between control wt and Cxcr4+/1013 mice at steady state and upon infection." (PMID 27111140, 2016). "Viruses using CCR5 as co-receptor are generally present in primary infections, whereas viruses using CXCR4 co-receptor emerge during later stages of infection, which is called as co-receptor switching." (PMID 25807147, 2015). "In contrast to the supporting role of N-glycan g15 for CCR5-specific infection, its presence interferes with CXCR4-specific infection." (PMID 25785610, 2015). "Non-selective purinergic receptors antagonists inhibited CCR5 and CXCR4-tropic HIV-1 productive infection in lymphocytes and CCR5-tropic virus in dendritic cells and macrophages." (PMID 26635799, 2015). "First, the C19+A8, C19+E6, C27+A8, and C27+E6 dual infections were added in equal “x4” titers (determined on U87.CD4.CXCR4 cells) to PBMC cultures in the presence of high maraviroc (MVC) concentrations." (PMID 26435727, 2015). "Initial HIV infection is considered to be facilitated via CCR5 coreceptor activity with evolution with CXCR4 during the later stage of infection." (PMID 24980635, 2014). "Since certain strains of both FIV and HIV use HSPG and CXCR4 for infection, it is attractive to design and synthesize heparin-derivatives or analogues that can work on both steps for HSPG and CXCR4 interaction with SU for HIV treatment." (PMID 25521480, 2014). "In fact, studies in mice and humans predict that these two antagonists would have opposite effects in human WNV disease, with Maraviroc promoting symptomatic disease and CXCR4 blockers promoting survival during infection." (PMID 25324719, 2014). "After infection of CXCR4-expressing cells with all recombinant viruses derived from JR-FLan/KI812.7, luciferase activities were ∼100-fold higher than those of CCR5-expressing cells." (PMID 24586840, 2014).
infection (continued). "CXCR4 is of more importance during later stages of infection and therefore CXCR4 is probably less important in LTNP." (PMID 25495598, 2014). "Since both TCA and FS FIV use receptor CXCR4 for entry and infection, we next examined the interference by heparin with the interaction between CXCR4 and TCA or FS FIV SU." (PMID 25521480, 2014). "Because CXCR4 is endogenously expressed on TZM-bl cells, it is susceptible to infection by diverse HIV-1 isolates." (PMID 24586238, 2014). "Other viruses including primary viral isolates and CXCR4-using HIV-1 have been used for infection of mucosal tissue and show similar or slightly better replication as compared to HIV-1BaL." (PMID 25025306, 2014). "U87.CD4.CXCR4.CCR5 cells express CD4, CCR5 and CXCR4 and are susceptible to infection by all investigated virus strains." (PMID 25499264, 2014). "This is, in part, due to the expanded repertoire of CXCR4-expressing T-cells available for infection." (PMID 23824043, 2013). "In order to investigate the exact mechanism underlying the increased susceptibility of PAMP-treated DCs to productive infection with X4 virus, we measured the surface expression of HIV-1 coreceptor CXCR4 after exposure to each agonist." (PMID 23844079, 2013). "The low expression of CXCR4 on DC would instead hamper their direct infection and favour the trans pathway." (PMID 23606583, 2013). "It is known that, with disease progression, viral variants emerge which infect host cells via a direct interaction with CXCR4 (CD134-independent infection)." (PMID 23992667, 2013). "Others tested a model for abortive infection of CXCR4+ tonsil CD4 cells where cytoplasmic viral DNA triggered a cell death pathway." (PMID 23742646, 2013). "Analysis of the microarray results for the signalling pathways highlighted different pathways in between LPAI- and HPAI-infected tracheas, with only the CXCR4 pathway present for both infections." (PMID 24015922, 2013). "We first choose as target PM1, a CD4pos T cell line known to be susceptible to infection by different HIV-1 isolates, including primary CCR5- and CXCR4-tropic tropic strains." (PMID 24330394, 2013). "In our study, the infection of duck tracheas with a HPAI- or a LPAI-H5N1 induced a different modulation of genes in the CXCR4 signalling pathway." (PMID 24015922, 2013). "Lower concentrations of AMD3100 were required to inhibit infection of cells expressing low levels of CXCR4 (MYA-1) than high levels of CXCR4 (CLL-CD134)." (PMID 23372784, 2013). "The results showed that both of the MVCs strongly inhibited infection of CXCR4 and CCR5-utilizing HIV-1 strains on T cells." (PMID 23884127, 2013). "To evaluate the contribution of a higher CXCR4 expression in the increase of cis-infection induced by PAMPs, we performed virus transfer experiments with DCs exposed to PAMPs for 3 days to allow an enhanced CXCR4 surface expression." (PMID 23844079, 2013). "CCR5-tropic viruses predominate in the initial stage of infection, whereas a switch from CCR5- to CXCR4-tropic viruses occurs in the late stages of infection in a subset of patients." (PMID 24147028, 2013). "In contrast, infection with the CXCR4-tropic SHIVmn229 resulted in a reduction in SerpinB2 mRNA levels in PBMCs; levels had fallen significantly by week 3 and remained depressed until week 11 (SHIV, p = 0.008 and 0.04, respectively)." (PMID 23460840, 2013). "Addition of the CXCR4 antagonist, AMD3100, 2 h post-infection resulted in complete loss of antiviral activity, while the non-nucleoside reverse transcriptase inhibitor (NNRTI) nevirapine kept its full activity when administered up to 4 h post-infection." (PMID 23724015, 2013). "We saw huge induction in the level of the chemokine receptor CXCR4 by both microarray and qRT-PCR post infection." (PMID 24278205, 2013).
infection (continued). "We next investigated the role of PDI and/or Trx in virus entry and infection of the T cell line, PM-1, which is known to naturally express both CXCR4 and CCR5 and can be infected with R5, as well as X4, HIV-1 strains." (PMID 23206338, 2012). "Several studies have shown that the CXCL12/CXCR4 axis is involved in the progression of diseases and infections." (PMID 22511975, 2012). "Only envelope 22-15-107 (from the spleen of subject 10017) conferred low levels of HIJ infection likely indicating CXCR4-use." (PMID 22420378, 2012). "Infection with HCMV induced upregulation of CXCR4 mRNA expression (p<0.001) at 8, 24, 48, and 96 hours post-infection." (PMID 23116176, 2012). "Second, viral particle-mediated induction of a signaling pathway via CXCR4 is required for infection of resting T cells." (PMID 22554282, 2012). "Infection with HCMV significantly increased the percentage of cells expressing CXCR4 and CXCR7 on the cell surface at all timepoints analyzed." (PMID 23116176, 2012). "Protein lysates were harvested at appropriate time points post-infection and equal amounts of total protein were subjected to Western blotting for CXCR4 and CXCR7." (PMID 23116176, 2012). "The fact that HIV selects two chemokine receptors, CCR5 and CXCR4, as the main entry coreceptors implies an urgent need for the virus to engage the chemotactic process to initiate infection." (PMID 22640593, 2012). "Expression of CCR5 and CXCR4 on CD4+ iNKTs makes them susceptible to infection with R5-tropic, X4-tropic, and primary isolate viruses, resulting in the preferential depletion of CD4+ iNKT cells during in vitro infection." (PMID 22916008, 2012). "Taken together, these data suggest that CB2R activation is altering a pathway specifically required for CXCR4-tropic infection." (PMID 22448282, 2012). "Gated CD11b+/Gr-1high neutrophils (R1) exhibited a significant reduction in CXCR4 levels at 12 and 24 h post infection." (PMID 23189271, 2012). "The CXCL12/CXCR4 axis thus appears to have a dual effect on the L. sigmodontis life cycle: by acting as a host-cell restriction factor for infection, and as a growth factor for worms." (PMID 22511975, 2012). "For three of these patient plasma samples, viral culturing was possible and viral coreceptor usage was confirmed by infection experiments of CCR5- or CXCR4-expressing U373 cells." (PMID 22493731, 2012). "It has also been suggested that the propensity of viruses establishing new infections to use the CCR5 coreceptor for host-cell entry is evidence of a transmission bias, since during the course of infection viruses typically evolve to use the CXCR4 coreceptor." (PMID 22593106, 2012). "Previously we reported that the proportion of pDC expressing IFN-α increased after infection with either CXCR4 or CCR5-tropic HIV-1." (PMID 21904619, 2011). "In a recent retrospective evaluation of a large number of patients (n = 390) enrolled in the PRIMO cohort in France between 1996 and 2007, a relatively high prevalence (15.9%) of predicted CXCR4-using viruses was documented during primary infection." (PMID 21284904, 2011). "In the case of HIV-1, the viral surface glycoprotein, gp120, can act as a ligand for CXCR4-dependent signaling and influence successful infection of target cells." (PMID 21949786, 2011). "We explored the evolution of CCR5 and CXCR4 use following 5P12-RANTES selection by evaluating single cycle infection mediated by CC1/85 env clones isolated after 13 (round 1), 25 (round 2), 30 (round 3), and 36–44 (round 4) weeks of virus replication." (PMID 21760945, 2011). "Only an isolate obtained from mandrills (SIVmnd;) and one from AGM (SIVagm.sab;) were found to use this coreceptor in addition to CCR5 for entry, and expansion to CXCR4-use was documented in two studies of SIVsm/SIVmac infection." (PMID 21284906, 2011).